LDHA (lactate dehydrogenase A)
Diseases named in the same sentence as LDHA in open-access papers (continued):
Sharing a sentence is not in itself a finding about the gene and the disease.
tumor (continued). "Hematoxylin and eosin (H&E) staining and LDHA immunohistochemistry confirmed reduced tumor burden and inhibition of glucose metabolism by the combination treatment." (PMID 40861817, 2025). "Among these, LDHA emerges as a key metabolic enzyme driving reprogrammed energy metabolism to support tumor growth." (PMID 41368023, 2025). "Lactylation genes, including LDHA, GLS1, and OGDH, are associated with poor immunotherapy results, are increased in malignancies, and contribute to the immunosuppressive tumor microenvironment." (PMID 39968078, 2025). "The oncogenic role of LDHA has previously been reported in numerous cancers, which can promote the malignant progression of tumor by increasing lactate production, accelerating glucose uptake and regulating several cancer-related molecules." (PMID 40464853, 2025). "The production of G-CSF and GM-CSF cytokines is suppressed, MDSC recruitment is limited, and anti-tumor immunity is strengthened when LDHA expression is decreased." (PMID 40230883, 2025). "Tumor growth was inhibited by LDHA KD in the subcutaneous transplantation model of HuH7 and Hepa1-6 KO cells." (PMID 40139191, 2025). "Elevated lactate levels, driven by enzymes like LDHA and monocarboxylate transporters (MCTs), correlate with increased tumor aggressiveness, angiogenesis, and poor survival." (PMID 41029427, 2025). "Using such approaches, researchers have detected the upregulated expression of various key glycolytic enzymes, such as hexokinase 2 (HK2), phosphoglycerate kinase 1 (PGK1), aldolase, and lactate dehydrogenase A (LDHA), in multiple tumor cell types." (PMID 40313939, 2025). "Nevertheless, emerging research suggests that even aggressive tumours can exhibit a metabolic shift towards OXPHOS when genetic disruptions of LDHA/B occur, which is crucial for tumour growth and progression." (PMID 39748215, 2025). "Inhibition of LDHA expressed significance in suppression of tumour progression and improvement of sensitivity for chemotherapy as well as radiotherapy." (PMID 40845073, 2025). ", proposed a novel metabolic engineering approach targeting lactate dehydrogenase A (LDHA) in the tumor microenvironment." (PMID 40768059, 2025). "Preclinical trials have demonstrated their significant efficacy in reducing tumor growth and inhibiting LDHA activity." (PMID 40959206, 2025). "Several effective LDH inhibitors have been identified; for instance, Oxamate acts as a competitive LDHA inhibitor by competing with pyruvate, thereby inhibiting tumor cell proliferation." (PMID 40443721, 2025). "As a key enzyme regulating glycolysis in tumor cells, LDHA is emerging as a promising and prospective focus in developing novel anticancer therapeutics overcoming drug resistance." (PMID 41561760, 2025). "In HBV-related HCC, viral proteins (e.g. HBx) have been shown to activate transcription factors such as NAC1, which drive LDHA expression and promote lactate production, immune escape, and tumor progression." (PMID 40717080, 2025). "In tumor cells, elevated lactylation enhances expression of glycolytic enzymes (e.g., LDHA, PKM2) and stemness-related genes (e.g., SOX2, NANOG), contributing to metabolic reprogramming and cancer progression." (PMID 41583433, 2025). "In the tumor microenvironment, LDHA-driven aerobic glycolysis is indispensable for NK cell activation and effector functions against malignant cells." (PMID 40498022, 2025). "Specifically, ALDH1A1 upregulates ZBTB7B in tumor cells, subsequently promoting the upregulation of LDHA." (PMID 39107297, 2024).
tumor (continued). "The evaluation of clinical samples using RT-qPCR found that the expression of LDHA was significantly higher in tumor tissues than in adjacent non-tumor tissues (P<0.001), which was further confirmed by protein blot analysis." (PMID 39680520, 2024). "As an vital enzyme index, LDHA has been shown to participate in the regulation of tumor formation, growth and metastasis." (PMID 39582531, 2024). "Tumor cells utilize lactate dehydrogenase (LDHA), a key regulatory enzyme of the glycolytic pathway, for lactate conversion from pyruvate." (PMID 38233415, 2024). "To further investigate the role of LDHA-mediated tumor-macrophage interplay in glioblastoma tumor biology, we utilized shRNA knockdown system to deplete LDHA in CT2A and GL261 tumors implanted into C57BL/6 mice." (PMID 38443336, 2024). "Inhibiting LDHA has been shown to slow down tumour growth and reduce the aggressiveness of tumour cells, highlighting the critical role of LDHA in tumour progression." (PMID 39021353, 2024). "Considering the central functions of lactate in immune suppression and tumor immune evasion, targeting lactate dehydrogenase A (LDHA) represents a promising strategy for enhancing the efficacy of cancer immunotherapy." (PMID 39766353, 2024). "The results demonstrated that LY2874455 (an FGF inhibitor) treatment notably suppressed tumor growth, improved the survival rate, and reduced the LDHA/LDHB ratio and serum lactate concentration." (PMID 38764020, 2024). "Reduction of LDHA function by small interfering RNA (siRNA) or a small-molecule inhibitor FX11 was proved to lead to tumor regression." (PMID 38396050, 2024). "ACYP1 exacerbates the Warburg effect through activation of the Myc/LDHA axis, contributing to its tumor-supportive effects." (PMID 39403606, 2024). "Numerous clinical retrospective studies have found that elevated levels of serum and bile lactate concentration and tumor LDHA expression are closely related to the pathological grading, clinical staging, and prognosis of GBC." (PMID 39010066, 2024). "The findings revealed a significant correlation between LDHA expression and tumor stage, indicating that elevated LDHA expression levels are indicative of more advanced tumor stages." (PMID 38993839, 2024). "Compared with the sh-NC group, the effect of anti-PD1 treatment in the sh-LDHA group was more significant, and the tumor reduction was more obvious." (PMID 38664705, 2024). "For instance, by inhibiting LDHA (lactate dehydrogenase A subunit) to reduce lactate production, it can help reverse the acidification of the tumor microenvironment and boost T cell activity." (PMID 39654883, 2024). "The LDHA inhibitor oxamic acid was shown to impede lactate accumulation and synergistically increase the anti-tumor abilities of other drugs, such as sorafenib, in cell line experiments." (PMID 38891772, 2024). "For instance, HIF-1α is activated in hypoxic conditions, increasing the expression of LDHA and enhancing glycolysis in tumor cells, which boosts their energy production and promotes proliferation and survival." (PMID 39609317, 2024). "In GBM, the Lactate Dehydrogenase A (LDHA) isoform is typically overexpressed, promoting the flux of substrates towards lactate production during glycolysis, enhancing tumor cell survival and proliferation." (PMID 39877360, 2024). "This hinders the conversion of pyruvate and CoA to acetyl-CoA in the mitochondria, increasing the flow of pyruvate towards conversion of lactate by LDHA, thus promoting aerobic glycolysis and tumor development." (PMID 39594816, 2024). "LDHA is a key enzyme in the final step of glycolysis, catalyzing the conversion of pyruvate to lactic acid, which in turn promotes Warburg effect and tumor growth." (PMID 38233839, 2024). "We conducted the ESTIMATE method and found that LDHA was negatively connected to stromal cells and immune cells in the tumor microenvironment." (PMID 39582531, 2024).
tumor (continued). "Taken together, these data provide a strong rationale for testing pharmacologic inhibition of LDHA to counteract tumor glycolysis and improve antitumor T cell function." (PMID 39225102, 2024). "The importance of targeting the isoform 5 of LDHA is gathered from studies on LDHA-deprived cancer cell lines suggesting that targeting hLDH5 can significantly prevent tumor growth and invasiveness, especially under hypoxic conditions." (PMID 38731601, 2024). "Lactate dehydrogenase (LDHA), a marker of tumor metabolism, is ubiquitously upregulated across the tumor tissue, with the most pronounced differences in the invasive regions." (PMID 39439806, 2024). "We demonstrated that USP11 overexpression promotes HIF‐1α stabilization and enhances glycolysis through PDK1 and LDHA‐related pathways, eventually leading to tumour cell proliferation and metastasis." (PMID 38229475, 2024). "APOL3 plays a role in the ubiquitination of LDHA, thereby increasing tumor cell sensitivity to the ferroptosis-inducing protein RSL3." (PMID 38853203, 2024). "Simultaneously, LDHA was positively associated with the infiltration levels of MDSC, resting mast cell, and resting NK cell that induces immunosuppressive tumor microenvironment and tumor immune escape." (PMID 39582531, 2024). "Among 17/22 (77.27%) TCGA pan-cancer datasets, the expression of LDHA was upregulated in tumor samples compared to normal samples." (PMID 38664705, 2024). "Increased levels of lactate and LDHA in tumours seem to indicate elevated levels of lactylation, and in experiments where lactate production inhibitors were used, lactylation levels were decreased." (PMID 39417674, 2024). "Since LDHA’s primary function is to generate lactate, and lactate as the final metabolite of the glycolytic pathway, it plays an important role in tumor progression and microenvironment regulation." (PMID 38233415, 2024). "Lactate dehydrogenase A (LDHA) is known to be highly expressed in glycolytic tumor cells, where it converts excess pyruvate and NADH into lactate and NAD+ to sustain the ATP-generating arm of glycolysis." (PMID 38216787, 2024). "Lactate dehydrogenase (LDHA), the glycolytic enzyme that catalyses the conversion of pyruvate to lactate, was one of the top upregulated proteins in resistant tumours." (PMID 38961290, 2024). "HK2 and LDHA mRNA expression levels were upregulated in OS tumor tissues, and their expression levels were negatively correlated with miR-577 expression." (PMID 38218855, 2024). "Deregulation of GLUT1, PFKFB3, and LDHA is known in many forms of cancers and facilitates the high glucose consumption by tumor cells." (PMID 39684459, 2024). "The antitumor activity of LDHi is dependent on tumor expression of LDHA and the adaptive immune system." (PMID 39225102, 2024). "Previous studies revealed that LDHA plays a vital role in tumor biology, including initiation, development, progression, invasion, metastasis, angiogenesis, and immune evasion, and targeting LDHA is considered a safe therapeutic strategy." (PMID 38664705, 2024). "KDM6B directly mediated the H3K27me3 demethylation of LDHA, with the result that the expression of lactate dehydrogenase LDHA was increased in OS cells, thereby promoting tumour metastasis." (PMID 38288377, 2024). "Current treatments targeting tumor lactic acid, including MCTs inhibitors and LDHA blockade, both show promise in suppressing tumor growth." (PMID 39091919, 2024). "APOL3 enhances the anti-tumor immune capacity of CD8+ T cells by promoting lactate dehydrogenase A (LDHA)-mediated ferroptosis." (PMID 39273090, 2024). "Particularly, small molecule inhibitors targeting lactate dehydrogenase A (LDH-A) can alter the tumor microenvironment, enhance the infiltration and function of immune cells, and provide new strategies for cancer treatment." (PMID 39654883, 2024).
tumor (continued). "HIF1 activates more than 100 downstream genes, commonly including vascular endothelial growth factor (VEGF), erythropoietin (EPO), GLUT1, and LDHA, regulating important biological processes required for tumor survival and development." (PMID 38715141, 2024). "Overcoming this will require the utilization of alternative diagnostics, such as targeted imaging (e.g., 18F-fluoroestradiol PET, magnetic resonance spectroscopy (MRS) to detect LDHA activity), and the detection of circulating tumor DNA (ctDNA)." (PMID 38553598, 2024). "ZBTB7B, a transcription factor of the rate-limiting enzyme LDHA involved in lactate production in glycolysis, emerges as a critical gene contributing to the failure of tumor cell immunotherapy." (PMID 39107297, 2024). "Consistent with in vitro results, combination treatments of HBO and CuET@PH NPs down-regulate the protein and gene expressions of GLUT1 and LDHA by overcoming tumor hypoxia." (PMID 38766644, 2024). "The LDHA inhibitor GSK2837808A within the nanosystem restricts glucose consumption in tumor, thereby creating a TME that is more favorable for CD8+ TILs." (PMID 39479443, 2024). "Developing inhibitors targeting key enzymes in lactate metabolism, such as LDHA, can reduce lactate production by tumor cells, thereby improving the tumor microenvironment and enhancing the infiltration and killing ability of immune cells against tumors." (PMID 39654883, 2024). "Western blot analysis illustrated that LY2874455 treatment restrained FGF1, FGF2, STAT1, and LDHA levels but increased LDHB levels in tumor tissues." (PMID 38764020, 2024). "Mechanistically, PCK1 destabilizes lactate dehydrogenase A (LDHA) through post-translational regulation, suppressing the Warburg effect and tumor progression." (PMID 39578429, 2024). "Targeting LDHA through its knockdown in glycolysis presents a potential therapeutic strategy to curb MDSCs recruitment, alleviate immunosuppression, and enhance tumor immunogenicity via the autophagy-related mechanism and DOX-induced ICD effects." (PMID 39479443, 2024). "GBM cells induce macrophages to infiltrate the tumor microenvironment by upregulating CCL2 and CCL7, and then macrophages promote tumor growth and survival by delivering LDHA to tumor cells." (PMID 39493751, 2024). "Positive staining of GLUT1 and LDHA was reduced in tumor tissues formed by C666-1 cells with ELF3 knockdown." (PMID 39219440, 2024). "Briefly, we found significant variations in LDHA expression between tumor and para-cancerous by pan-cancer analysis, and revealed the relevance of its expression to clinical prognosis." (PMID 38709280, 2024). "The present study proposes a novel strategy for the treatment of GBM, which targets the LDHA-mediated tumor-macrophage symbiosis." (PMID 39493751, 2024). "LDHA inhibitors can not only regulate the inhibitory anti-tumor immune function of macrophages but also inhibit the growth and development of tumors." (PMID 39464313, 2024). "For example, it has been found that elevated expression of LDHA was positively correlated with tumor size, clinical stage, and histological grade, and that its elevated expression was associated with poor prognosis in cancer patients." (PMID 38567310, 2024). "MCF-7 and MCF-7 TamR BC cell lines, as tamoxifen sensitivite and resistance in vitro models, were used to explore the correlation between FASN/LDHA expression and tumor aggressiveness." (PMID 39044184, 2024). "Due to the permanent deficiency of LDHA, the development of effector CD8+ T cells with strong anti-tumor activity is hindered." (PMID 39464313, 2024). "Previous research has also used experiments with LDHA inhibitors, enhancing the anti-tumor activity of CD8+ T cells." (PMID 39343933, 2024). "We discovered that the expression levels of LDHA were significantly higher in tumor tissues compared to normal tissues (P<0.001)." (PMID 39680520, 2024).
tumor (continued). "Lactate dehydrogenase A (LDHA) is a crucial enzyme involved in both glycolysis and gluconeogenesis that plays a fundamental role in modulating tumor resistance to pharmacological interventions." (PMID 39403606, 2024). "The team further determined that both genetic and pharmacological blockade of LDHA-mediated tumor-macrophage symbiosis both suppressed macrophage infiltration in murine GBMs as well as reduced tumor progression." (PMID 38994360, 2024). "LDHA expression is elevated in a variety of malignancies and is thought to be a metabolic adaptation of tumor cell glycolysis." (PMID 39587076, 2024). "LDHA has been reported to regulate HCC tumor growth and metastasis by inducing MMP-2 production, which leads to apoptosis by inhibiting the production of reactive oxygen species (ROS)." (PMID 38291366, 2024). "The suppression of glycolytic activity by different kinds of inhibitors or LDHA knockdown contributed to the anti-tumor effects of PDAC in vitro and in vivo." (PMID 38711083, 2024). "Research indicates that LDHA is overexpressed in several tumor cells, and its inhibitory effects can significantly slow down tumor progression." (PMID 38841361, 2024). "This study aims to verify LDHA’s expression and metabolic impact in human LUAD and understand the role of LDHA in tumor treatment and drug sensitivity in LUAD cells." (PMID 39680520, 2024). "A newly developed LDHA inhibitor, ML-05, effectively decreases lactate synthesis, leading to both tumor growth inhibition and enhanced antitumor immune responses of CD8+ T cells." (PMID 39766353, 2024). "LDHA expression was connected to multiple tumor-infiltrating lymphocytes (TILs), m6A-related genes, and ferroptosis-related genes." (PMID 39582531, 2024). "Pan-cancer analysis revealed that the significant correlations existed between LDHA expression and tumor microenvironment (including stromal cells and immune cells) as well as stemness scores (DNAss and RNAss) across cancer types." (PMID 38709280, 2024). "In hypoxia, the expression of the glycolytic genes PKM2 (pyruvate kinase M2), HK2 (hexokinase 2), and LDHA (lactate dehydrogenase A) is upregulated, which promotes glycolysis in tumor cells." (PMID 38491378, 2024). "In our study, nuclear PKM2 acted as a protein kinase, promoting the phosphorylation of STAT3, thereby regulating the expression of downstream glycolysis-related genes such as GLUT1, ENO1, and LDHA, which in turn promotes tumor progression." (PMID 39368995, 2024). "The expression levels of GLUT-1 and LDHA in tumor cells and the level of lactate in the TME are closely related to the antitumor immune effect of the body." (PMID 39408814, 2024). "Simultaneously, we also explored the correlation between differential expression of LDHA and various tumor outcomes." (PMID 38709280, 2024). "RNA-seq re-validation confirmed that ZBTB7B knockdown resulted in reduced expression levels of LDHA and PD-L1 in tumor cells, establishing LDHA and PD-L1 as downstream effectors of ZBTB7B." (PMID 39107297, 2024). "In our study, we analyzed the link of LDHA expression with tumor prognosis or the immune system based on a series of databases." (PMID 38709280, 2024). "Lactate produced by LDHA contributes to tumor progression, angiogenesis, and immunosuppression and is believed to be a vital regulator of tumor development, maintenance, and metastasis." (PMID 38993839, 2024). "LDHA expression showed tumor heterogeneity, and it has the potential to be an independent prognostic factor for many tumors." (PMID 38709280, 2024). "The relationship between LDHA expression and immune infiltration was explored by Tumor Immune Estimation Resource 2.0 and Gene Expression Profiling Interactive Analysis." (PMID 39582531, 2024). "The isoenzyme in lactate dehydrogenase: lactate dehydrogenase A. LDHA exist more abundantly in tumor tissues than in normal tissues." (PMID 38525419, 2024).